IFNG (interferon gamma)
Diseases named in the same sentence as IFNG in open-access papers (continued):
Sharing a sentence is not in itself a finding about the gene and the disease.
melanoma (continued). "Because DC have been shown to be potent inducers of NK cell activation by elevated expression of activation markers as well as enhanced IFNγ secretion, lytic activity and proliferation, we investigated whether the DC ± IFNα strategy also enhanced NK cell activity in melanoma patients." (PMID 30761123, 2019). "These cells were naïve to immune checkpoint inhibitors, and we examined whether the expression of key IFNγ downstream targets [PD-L1, PD-L2, nerve growth factor receptor (NGFR), HLA-A, -B, -C, and HLA-DR] could serve to assess the integrity of IFNγ signaling in melanoma." (PMID 29977240, 2018). "Based on this knowledge, we postulated that melanoma cells from patients responding to immunotherapy should be sensitive to the anti-proliferative and pro-apoptotic effects of IFNγ and that continuous cytokine exposure should select for the outgrowth of IFNγ-resistant tumour subclones." (PMID 28561041, 2017). "Since potent IFNγ production is associated with enhanced antitumor responses, we examined whether CXCL16 co-stimulation of iNKT cells during glycolipid activation modified tumor clearance in an experimental model of B16-F10 melanoma metastasis to the liver." (PMID 27471636, 2016). "Furthermore, these data suggest that HLA-DR expression in melanoma cells may be a biomarker for tumours primed with activated T-cells and an appropriate IFNγ response to mediate sensitivity to PD-1/PD-L1 blockade." (PMID 26822383, 2016). "Since IFNγ upregulates PD-L1 expression by melanoma cell lines, we assessed whether concomitant treatment of melanoma cells with IFNγ and PD-1 inhibitory antibody resulted in further enhancement of T-lymphocyte lysis by T-lymphocyte clones specific for the IP processed the NY-ESO-192–100 epitope." (PMID 26885372, 2016). "Moreover it was shown in the same studies that PD-L1 could be up-regulated on melanoma by exposure to interferon gamma (IFN-γ)." (PMID 25844720, 2015). "Interestingly, the effect of IFNγ on melanoma B16F10 cells was remarkable." (PMID 25428727, 2014). "Interestingly, fludarabine was efficient in suppressing protein expression and consequently IDO activity in two different cell lines derived from breast cancer and melanoma when IDO was activated with interferon-gamma (IFN-γ) or supernatants prepared from activated T lymphocytes." (PMID 24911872, 2014). "Additionally, we investigated whether IFNγ produced by IFNγ-ADSCs can activate the JAK/STAT1 dependent signaling pathway in melanoma cells." (PMID 25428727, 2014). "Additionally, we confirmed IFNγ-induced overexpression of PD-L1 in melanoma tumor cells." (PMID 25428727, 2014). "Furthermore, when human monocyte-derived DCs and irradiated melanoma cells were co-incubated with T cells, T cell-derived IFNγ secretion increased, an observation that was also substantiated in vivo when irradiation of established B16F10 tumors resulted in an increase of IFNγ-producing spleen cells." (PMID 24376443, 2013). "Our ligand-receptor-based cell communication analysis demonstrated increased interactions between ETV4-low melanoma cells and T cells, including TNFSF14-LTBR and IFNG-(IFNGR1+IFNGR2) signaling pathways." (PMID 41502516, 2025). "These phenotypes, covering more than 70% of all melanoma cases, all displayed IFNγ‐induced MHC II upregulation and developed resistance to NKmK upon IFNγ exposure, thus highlighting the relevance of MHC II in NKmK." (PMID 41078003, 2025). "Given this important finding, we next determined IFNγ secretion in co‐culture conditions (4 h) in which we exposed NK‐naïve (control) and NK‐exposed (co‐cultured) 1205Lu and WM793 melanoma cells to fresh primary NK‐cells." (PMID 41078003, 2025). "IFNγ plays a crucial role in inhibiting tumor growth, enhancing MHC expression, and limiting angiogenesis in cancers such as brain tumors, melanoma, and colon cancer." (PMID 41019045, 2025).
melanoma (continued). "Interestingly, we noted that T cells overexpressing the full-length Siglec-7 receptor demonstrated a 30-50% reduction in IFNγ secretion in co-cultures with melanoma cell lines (*p<0.05; 624.38 and 888/A2), suggesting that Siglec-7 may fulfill an inhibitory function in primary human T-cells." (PMID 40433387, 2025). "Consistently, treatment of differentiated melanoma cell lines with a DNMT inhibitor induced global DNA de-methylation, promoted de-differentiation and upregulated viral mimicry and IFNG predictive signatures of immunotherapy response." (PMID 40682094, 2025). "Flow cytometric analysis revealed that in the activated state, the proportion of IFNγ+CD8+ T cells and GZMB+CD8+ T cells was significantly increased in PBMCs co-cultured with Vin-treated melanoma cells." (PMID 40866941, 2025). "To that end, we generated conditioned media of melanoma cells treated with solvent control, inhibitors of IDO1 or GLI alone or in combination with IFNγ (to induce IDO1 expression and kynurenine production)." (PMID 39962447, 2025). "The performance of PSMB9 in the melanoma cohort was comparable to that of previously reported signatures such as T cell-inflamed GEP, TAM M2, IFNG, CD8, and CD274, which all showed an AUC more than 0.8." (PMID 41020834, 2025). "Since CD99 signaling can be initiated by other tumor components, in addition to melanoma cells (predicted to generate the strongest signals), we focused our analysis on CRTAM and IFNγ expression in NK‐cells." (PMID 41078003, 2025). "In human melanoma cells, inhibition of GLI1 expression prevented the induction of IDO1 expression in response to IL6/STAT3 and IFNγ/STAT1 signaling." (PMID 39962447, 2025). "Thus, NK cluster 01 subtype cells have the greatest potential for regulating CM malignant cells through the tumor necrosis factor (TNF)–TNFRSF1B axis, suggesting that NK cluster 01 cells may respond to melanoma cells by producing proinflammatory cytokines, including IFNγ and TNF." (PMID 41357561, 2025). "NRP1 is a transmembrane glycoprotein that has been shown to affect IFNγ signaling in endothelial cells, and is furthermore negatively regulated by MITF in melanoma cells." (PMID 39736644, 2024). "IFI30 expression can induce other cell types through interferon-gamma (IFN-γ), such as melanoma cell lines." (PMID 37991414, 2024). "For the in vitro models, we analyzed the B16 (mouse melanoma), EMT6 (mouse breast cancer), KPC (mouse pancreatic cancer), and MC38 (mouse colon cancer cells) models treated with IFNβ, IFNγ, and TNF-α." (PMID 38590654, 2024). "This clearly indicates that increased PD-L1 expression following IFNγ treatment and MITF knockdown, as well as the crosstalk between IFNγ and MITF expression in melanoma cells, is context-dependent." (PMID 39736644, 2024). "In melanoma patients, serum derived exosomes expressing CD73 suppress interferon gamma (IFN-γ) production, impairing T cell function." (PMID 39724442, 2024). "It is plausible that melanoma cells at varying stages of differentiation will show different responses to the combination of MITF knockdown and IFNγ stimulation." (PMID 39736644, 2024). "As our results indicate that dedifferentiation affects IFNγ-induced PD-L1 expression in a context-dependent manner in 624Mel cells and is not observed in our other melanoma cell lines, we asked the question whether this trend is noticeable in a wider context of melanoma cases." (PMID 39736644, 2024). "We further validated our results by treating other human melanoma cell lines, WM1361A and WM793, with IFNγ and NextA." (PMID 38414061, 2024). "However, whether NRP1 affects IFNγ signaling in melanoma cells is unknown." (PMID 39736644, 2024). "We interpret these results as evidence that impaired IFNγ production by dysfunctional TIL limited the expression of MHC-I and MHC-II on B16 melanoma tumor cells, hindering efficient clearance of melanoma cells in obese mice." (PMID 38565540, 2024).
melanoma (continued). "Dedifferentiation of melanoma cells was induced via either siRNA or shRNA mediated MITF knockdown and the cells were subsequently treated with IFNγ." (PMID 39736644, 2024). "Our result demonstrated CAR-T cell-specific activity reflected by the elevation of both interferon-gamma and Granzyme B in EpCAM+ gastric-PDXO-GA0091 co-culture as compared to the EpCAM- melanoma PDXO-ME1154 co-culture." (PMID 36602988, 2023). "Taken together, our data suggest that PD-1 regulates IFNγ production and type 1 ILC phenotype within the melanoma TME." (PMID 37098069, 2023). "In the second experiment, we tested EpCAM-CAR-T cells co-cultured with EpCAM+ gastric PDXO-GA0091 and EpCAM- melanoma PDXO-ME1154, and measured the interferon-gamma and Granzyme B levels in the culture." (PMID 36602988, 2023). "In melanoma, knockdown of FTO promotes YTHDF2-mediated PD-1, CXCR4, and SOX10 mRNA decay, sensitizing melanoma cells to interferon-gamma and anti-PD-1 therapy." (PMID 36859310, 2023). "Theproportions of IFNγ+, TNFα+, andGzmB+ pmel-1 T cells in B16F10 melanoma tumor tissues weredramatically increased using this strategy." (PMID 37901179, 2023). "We also included signatures of T effector, IFNG, 6-gene GEP, 18-gene GEP, pan-fibroblast TGFβ response signature (F-TBRS), TLS and TLS in melanoma (TLS_M)." (PMID 37492578, 2023). "Deletion of SHP-2 in myeloid cells curbs B16 melanoma growth and boosts tumor concentrations of chemoattractant CXCL9, macrophage-produced IFNγ-induced CXCL9, and CD8+ T cell infiltration into tumors." (PMID 38022587, 2023). "Oncoplot further showed that tumors with T cell-inflamed signatures clustered together with higher IFNγ scores and significantly correlated in PCM, MBM, and ECM, which has been demonstrated in melanoma and other tumor types." (PMID 37964004, 2023). "Initially, the cytokine IFNγ was identified to be primarily secreted by CD8+ T cells and known to affect the dedifferentiation degree of melanomas cells." (PMID 37182170, 2023). "As was observed for melanoma cells, IFNγ treatment of Ptpn2 knockout CT26 and MC38 cells enhanced the expression of the IFNγ response genes Cxcl1, Ccl5, Stat1, Stat2, Stat3, Irf1, Pd-l1, Tap1, and Casp8, compared with IFNγ-treated control cells." (PMID 36968224, 2023). "While some cancers do not express MHC class II molecules and thus cannot be directly recognized by CD4 T cells, human melanoma, MCC, and murine B16F10 cells can express MHC class II molecules, with upregulated expression observed in the presence of IFNγ." (PMID 37711623, 2023). "For example, depletion of Mettl3/14 strengthens the response to anti‐PD‐1 therapy by promoting interferon-gamma (IFN‐γ)‐Stat1‐Irf1 signaling in CRC and melanoma." (PMID 36960074, 2023). "RNA-seq analysis revealed upregulation of PARP14 expression in multiple human and mouse tumour cell lines chronically exposed to IFNγ as well as in IFNGhigh melanoma tumours, suggesting that PARP14 is an IFNγ target gene." (PMID 37752135, 2023). "IFNγ was proposed to be an important marker of response to ICB in lung cancer and melanoma patients." (PMID 36564823, 2022). "To identify the conservation of the IFNγ response, we analyzed RNA-seq of additional murine solid tumors treated with IFNγ, including B16F10 (melanoma) and MC38 (colon adenocarcinoma), which revealed concordant transcriptional responses across all cell types." (PMID 35902886, 2022). "In melanoma, Yang and colleagues found FTO played a crucial oncogenic role in promoting tumorigenesis and resistance to interferon gamma and anti-PD-1 treatment." (PMID 35961973, 2022). "Compared with TIDE, MIS score, CD274, CD8, IFNG, T.Clonality, B.Clonality, and Merck18, DDX20 alone had a higher AUC (0.62) in melanoma (Riaz2017_PD1_Mealnoma_lpi.Navie)." (PMID 36246406, 2022).
melanoma (continued). "It was proved that CTLs-mediated cytotoxic function in melanoma and other cancers depends on a SOCE-mediated [Ca2+]I rise by regulating the degranulation of CTLs, the production of TNFα and IFNγ, and the expression of Fas ligand both in vivo and in vitro." (PMID 35162934, 2022). "The IFNγ signaling signatures has also been found to be highly correlated with the response to ICI in diverse tumors, including melanoma." (PMID 35837286, 2022). "Compared with TIDE, MSI score, CD274, CD8, IFNG, and Merck18, DDX20 alone had a higher AUC (0.68) in melanoma (Liu2019_PD1_Mealnoma_lip_Naive)." (PMID 36246406, 2022). "The results indicated that high expression of PROM2, EGFR, AURKA, and low expression of IFNG, ARNTL, FBXW7 correlated with a poor prognosis of melanoma patients." (PMID 35692844, 2022). "Compared with TIDE, CD8, IFNG, T.Clonality, B.Clonality, and Merck18, DDX20 alone had a higher AUC (0.65) in melanoma (Nathanson2017_CTLA4_Mealnoma_Pre)." (PMID 36246406, 2022). "Instances include HER2+ markers and interferon gamma response in GSE75688 breast cancer data (cluster 2), and SOM D markers and epithelial-mesenchymal transition in GSE81383 melanoma data (cluster 3)." (PMID 35665803, 2022). "In addition, analysis of PD-L1 expression in a panel of melanoma cell lines confirmed the hypoxic induction of Pd-l1 mRNA expression in murine B16 cells, but also revealed that hypoxia differentially regulates (IFNγ-induced) PD-L1 expression in a panel of human melanoma cell lines." (PMID 34268602, 2022). "Melanoma cells are cultured with autologous TILs to identify known mechanisms of ICI resistance, such as impaired IFNγ-JAK/STAT and antigen presentation pathways, as well as novel mechanisms such as CD58 downregulation." (PMID 36479127, 2022). "After intra-tumoral injection with C. acnes, the growth of melanoma cells was inhibited through the induction of Th1 type cytokines such as IL-12, tumor necrosis factor alpha (TNF-α), and interferon gamma (IFN-γ)." (PMID 35163734, 2022). "Cells with high basal MHC-I such as MC-38 and B16 melanoma showed a weak response to platinoids alone but that response, including Nlrc5 mRNA and surface MHC-I, was augmented by IFNγ." (PMID 33602823, 2021). "Overall, our findings demonstrate that IL-17 collaborating with IFNγ to induce TA-MSC transformation, which can be targeted by RA for melanoma treatment." (PMID 33889575, 2021). "We simultaneously supplied RA during IL-17 and IFNγ mediated TA-MSC transformation, and further performed co-engrafted cell-derived xenograft experiments with B16F0 melanoma cells and transformed TA-MSCs or RA treated TA-MSCs." (PMID 33889575, 2021). "In melanoma patients, a GEP indicative of interferon gamma signaling was shown to be predictive of improved ORR and PFS to PD-1/PD-L1 blockade." (PMID 33916348, 2021). "As for anti-PD-1 blockade, the IFN-γ gene signature (IDO1, CXCL10, CXCL9, HLA-DRA, STAT1, and IFNG) predicts the response to anti-PD-1 therapy in multiple tumors, including melanoma." (PMID 34439264, 2021). "Our study revealed that IL2RA、IL2RG, IFNG, and IL7R were hub genes in melanoma metastasis and involved in JAK—STAT signaling pathway that was identified as an central signaling pathway in metastatic melanoma, which was rarely illustrated in previous studies." (PMID 34159752, 2021). "The increased density of CTLA-4 on the melanoma cells is due to the activation of the JAK1/2 pathway, mediated by interferon-gamma (IFN-γ)." (PMID 33692796, 2021). "gCpG based tumor vaccine inhibited both primary and metastasis of melanoma in mice which was dependent on CD8 + T cells and IFNγ." (PMID 34794428, 2021). "Proinflammatory cytokines, such as interferon-gamma (IFNγ) and tumor necrosis factor-alpha (TNFα), and epigenetic modulators, such as histone deacetylase (HDAC) inhibitors, can induce CD40 expression on melanoma cells." (PMID 34092233, 2021).
melanoma (continued). "We obtained with our protocol numerous pure M1-CTLs which were producing high amounts of IFNγ, TNFα and IL-2, and were able to specifically lyse both MART-1-pulsed T2 cells and melanoma-derived cell lines very efficiently, with a high functional avidity." (PMID 34566953, 2021). "PD-L1 is regulated by interferon-γ (IFNγ) signaling and displays interferon regulatory factor 1 (IRF1) binding at its promoter, as described in melanoma cells and other cancer entities." (PMID 34689158, 2021). "And regulatory T‐cell proportion was indeed critically elevated in metastatic melanoma relative to primary melanoma, as well as in highly expressed IL2RA, IL2RG, IL7R, and IFNG group than their respective counterparts." (PMID 34159752, 2021). "Another relevant finding in this study was that overexpressed Treg cells in metastatic melanoma as compared with that in primary melanoma, were the pivotal intermediate components by which IL2RA, IL2RG, IL7R, and IFNG exert their immunosuppressive effect." (PMID 34159752, 2021). "Secretion of IFNγ and IL-12 and other inflammatory cytokines via TLR7/8 stimulation enabled NK cells to kill HNSCC and melanoma B16 tumor cells while TLR9 triggered cytotoxic activity of these cells on melanoma cells." (PMID 34124272, 2021). "In MMTV-Erbb2 breast, MC38 colon, and B16-F10 melanoma tumor models, CDK4/6 inhibition led to a decrease in total numbers of CD3+ tumor infiltrating T cells, encompassing CD8+ T cells and Granzyme B+ and IFNγ+ cells." (PMID 34025662, 2021). "In one study, LSECtin was expressed on murine B16 melanoma cells: interaction between LSECtin and LAG3 led to inhibition of Interferon γ (IFNγ) secretion by CD8 T cells and reduced their cytotoxic activity, promoting tumour growth." (PMID 34503258, 2021). "Collectively, our findings underscored the core position of IL‐2RA, IL‐2RG, IFNG, IL‐7R, and JAK—STAT pathway in melanoma metastasis." (PMID 34159752, 2021). "In contrast, ML NK cells from the same HD had significantly increased IFNγ, TNF, and CD107a expression after restimulation with DM6 and M14 melanoma cells." (PMID 34187852, 2021). "NK cells from melanoma patients showed impaired activation of STAT1, a critical molecule in the IFNγ-mediated signaling pathway, after IL2 stimulation." (PMID 33809795, 2021). "This indicated that IL-17 incorporated with IFNγ to stimulate the BMSC to TA- MSC transformation, which promoted tumor growth in melanoma." (PMID 33889575, 2021). "Wnt/β-catenin signaling in melanoma cells promotes immunological tolerance by limiting DC maturation, promoting IDO production, and suppressing IFNγ production by CTLs." (PMID 32117236, 2020). "Perhaps the expression of IFNG can be combined with TMB and PD-L1 to construct a more accurate prediction model for immunotherapy in melanoma." (PMID 33072607, 2020). "Cellular activity was determined by measuring inhibition of Trp-catabolizing activity in the human A375 melanoma cell line, which expresses IDO1 after stimulation with IFNγ." (PMID 33584686, 2020). "We treated melanoma cells with either decitabine (DAC), a DNA methyltransferase inhibitor, known to reactivate epigenetically silenced genes, or with interferon gamma (IFNγ), known to upregulate antigen presentation." (PMID 32157095, 2020). "The same treatment regimen of IDO1/AhR inhibitor with IFNγ reduced tumor growth and prolonged the overall survival of NOD/SCID mice bearing B16 melanoma tumors." (PMID 33379189, 2020). "Intranasal Mn2+ administration showed a significant synergic effect on restricting B16 melanoma growth in mice with greatly increased CD8+ TILs and IFNγ+CD8+ TILs." (PMID 32839553, 2020). "Next, we tested if the 36 active compounds from the IFNγ HTRF assay and the cell viability assay can affect expression of genes that regulate melanoma cells differentiation and pigmentation such as MITF, DCT, Melan-A and Tyrosinase-related protein 1(Tyrp)." (PMID 32231230, 2020).